IL1B (interleukin 1 beta)
Diseases named in the same sentence as IL1B in open-access papers (continued):
Sharing a sentence is not in itself a finding about the gene and the disease.
diabetes (continued). "Calorie restriction and exercise-mediated weight loss decreased mRNA levels of NLRP3 and IL-1β, and improved insulin sensitivity in diabetic subjects, demonstrating that pyroptosis contributes to the pathogenesis of IR and diabetes by mediating inflammation and β-cell destruction." (PMID 36009329, 2022). "IL-1β plays an important role in metabolic disease and the development of diabetes that were supported in studies with a deficiency of mature cytokine or signaling leading to insulin resistance and the inhibition of IL-1β-mediated action that was shown to improve pancreatic beta-cell function." (PMID 36014927, 2022). "The values of evaluated pro-inflammatory cytokines, tumour necrosis factor-α (TNF-α), interleukin-6 (IL-6), and interleukin-1β (IL-1β), assessed from the ascending aorta were elevated by all three cardiovascular risk factors, with the highest levels induced by type 1 diabetes mellitus (up to 259%)." (PMID 35163364, 2022). "Proinflammatory cytokines including TNF-α, IL-6 and IL-1β are notable cytokines that rapidly responds to oxidative damages and they have been extensively implicated in central and peripheral inflammatory reactions in diabetes." (PMID 34733158, 2021). "The results showed that guava juice and trehalose could inhibit the secretion of IL-1β in the pancreas and kidneys caused by diabetes, and could prevent apoptosis and pyroptosis." (PMID 33692782, 2021). "However, when the diabetic mice were treated with an antisense oligonucleotide (ASO) to APOC3 in vivo, the increased macrophage cholesteryl ester loading associated with diabetes was prevented while the heightened Il1b and Tnfa gene expression was unaffected." (PMID 32118048, 2020). "However, excessive or chronic inflammasome activation and subsequent interleukin-1β (IL-1β) release are implicated in the pathogenesis of various autoimmune diseases such as rheumatoid arthritis, inflammatory bowel disease, and diabetes." (PMID 33424869, 2020). "A hallmark of T2DM is the occurrence of IAPP-derived amyloid aggregates in the pancreatic islets, which is associated with β-cell toxicity and inflammasome-mediated IL-1β production and inflammation, leading to the characteristic loss of β-cell mass in type 2 diabetes mellitus." (PMID 32131431, 2020). "Increased circulating IL-1β level is associated with cognitive impairment in diabetes." (PMID 33379163, 2020). "In addition to its role on inflammation, IL-1β is involved in endothelial dysfunction, a hallmark of several cardiovascular and metabolic diseases, including diabetes." (PMID 32009974, 2019). "Elevated levels of IL-1β increase diabetes susceptibility through increased insulin resistance." (PMID 30116147, 2018). "Aberrant activation of the innate immune system, including NOD-like receptor pyrin domain containing 3 (NLRP3) inflammasome-dependent interleukin-1β (IL-1β) secretion, has been implicated in the pathogenesis of type 2 diabetes mellitus (T2DM) and its complication." (PMID 28970837, 2017). "In fact, several studies have also reported the regulatory roles of T-helper cell cytokines in multiple low doses of streptozotocin (MLD-STZ) diabetes model, suggesting the pathogenic role of IL-17 and IL-1β and protective role of IL-6, IL-10, and IL-4 in MLD-STZ mice." (PMID 29317893, 2017). "Wogonin has been proved to mitigate inflammation, hyperglycemia, and dyslipidemia, exerting beneficial effects on diabetes and diabetes-associated diseases with elevated adiponectin expression, decreased IL-1β, IL-6, and TNF-α production, and inhibited Th17 differentiation and NF-κB signaling." (PMID 28736524, 2017). "In the retina and kidneys of WT mice with diabetes, increased expression of inflammatory markers (IL-6, TNFα, IL1β) in association augmented expression of ECM proteins (collagen 1αIV, fibronectin) and NF κB-P65 were observed, compared to WT non-diabetic controls." (PMID 28301595, 2017).
diabetes (continued). "In addition, we carried out antibody-based blockade of Il-1β and Tlr4 to validate the association of these macrophage-related molecules with diabetes-induced Lgals1 expression in the mouse retina." (PMID 29170525, 2017). "Recent study suggested that EC damage in diabetes might be linked to the mechanisms triggered by IL-1β and recovered by IL-1 receptor antagonist." (PMID 26944557, 2016). "The close association between TLR2 activation and IL-1β secretion and their influence on arrhythmogenesis indicates that TLR2 and IL-1β are part of an inflammatory pathway that has a major role in the pathogenesis of diabetes-associated electric dysfunction of the heart." (PMID 27882934, 2016). "In addition to its key role in vascular disease, IL-1β has been implicated in the pathogenesis of type 2 diabetes mellitus (T2DM)." (PMID 27737744, 2016). "PCA component 2 (in which IL-6, IL-1β, and IL-8 loaded highly) was significantly associated with poorer gingival condition (OR 1.60, 95% CI 1.09–2.34; p-value 0.016) after adjustment for age, duration of diabetes, HbA1c, BMI, and sex." (PMID 25915398, 2015). "Additionally, diabetes is associated with high levels of blood cytokines including IL-1β, IL-6, IL-12, IL-17, IL-18, TNF-α and IFN-γ, which mediate the physiological adaption of insulin production and insulin resistance." (PMID 26684748, 2015). "Several IL-1β blocking monoclonal antibodies are currently being developed for autoimmune disorders including rheumatoid arthritis, cryopyrin-associated periodic syndrome, diabetes, and gout." (PMID 26251696, 2015). "When stratified by diabetes status (interaction p-value, < 0.001 to 0.99), associations for those without diabetes were also generally null, with the exception of significant inverse associations with nearly all exposure windows for IL-1β." (PMID 22336131, 2012). "Our observations indicated that formononetin could protect against pancreatic β-cell apoptosis caused by IL-1β and therefore could be used in the future as a new drug improving diabetes mellitus." (PMID 22922276, 2012). "Similarly, IL-1β, released by immune cells in response to bacterial infection in periodontitis, contributes to the breakdown of the periodontal ligament and alveolar bone, while in diabetes, it is implicated in beta-cell dysfunction and insulin resistance." (PMID 40283848, 2025). "Moreover, at baseline, LDL/ATP-induced WAT IL-1β-secretion was associated in the direction of higher diabetes risk in subjects with high-apoB, associating negatively with 1st phase and total DI, IS, and WAT PPARG mRNA and positively with SREBP2 mRNA and android fat." (PMID 39511203, 2024). "In this study, we found that MCC950 reduced macrophage pyroptosis, suppressed IL-1β secretion, and ameliorated alveolar bone loss, suggesting that targeting inflammasome-mediated inflammation is a novel therapeutic strategy for the treatment of diabetes–periodontitis." (PMID 37047282, 2023). "miR-29ab1 plays a crucial role in diabetes-related macrophage inflammation, and ectopic increases in miR-29a and miR-29b1 in diabetic skin wounds are associated with upregulation of M1 polarization and IL-1β, compared with healthy subjects, as well as with elevated TNF-α levels." (PMID 36601058, 2022). "Many chronic illnesses including endothelial dysfunction, diabetes mellitus, cardiovascular diseases, malignancy, autoimmune disorders which, as shown in the studies, were associated with vitamin D were also similarly associated with adropin, IL-1β, IL-6 and oxidative stress." (PMID 36326375, 2022). "We measured traditional CVD risk factors [blood pressure, Body Mass Index (BMI), diabetes, age, sex, smoking], serum markers of systemic inflammation (hsCRP, GlycA) and metabolic dysfunction (cholesterol efflux capacity), and inflammatory cytokines (IL-1β, IL-6, IL-12/IL-23, IL-17A, TNF-α, IFN-γ)." (PMID 35720288, 2022).
diabetes (continued). "Also, the blockade of the Casp-1/IL-1β pathway may prevent Müller cell loss induced by diabetes, indicating that the pyroptotic process may be responsible for Müller cell death." (PMID 34877938, 2021). "Similarly, effects on glucose metabolism, insulin resistance, pancreatic β cell function and risk of diabetes are attributed to elevations in TNFα and IL-1β, whilst IL-1β antagonism reduces hyperglycaemia and improves pancreatic β cell function in patients with T2D." (PMID 32907617, 2020). "The association of Metrnl with hs‐CRP (r = −0.141; P = 0.009), IL‐1β (r = −0.240; P = 0.002), and IL‐11 (r = 0.178; P = 0.025) remained statistically significant even after adjustments for age, sex, smoking, alcohol intake, diabetes, BMI, Cr, FBG, TC, TG, and LDL‐C." (PMID 30394666, 2019). "In addition to TNFα, the proinflammatory cytokine, IL-1β, has been implicated in diabetes." (PMID 30116147, 2018). "Moreover, IL-1RI-deficient mice are protected from diabetes-induced retinal pathology, indicating that IL-1β signalling may play a key role in the development of diabetic retinopathy." (PMID 28588350, 2017). "Treatment of patients with diabetes and periodontal disease with topical melatonin was associated with a significant improvement in the gingival index and in pocket depth, and a statistically significant reduction in concentrations of IL-1β, IL-6 and PGE2 in gingival crevicular fluid." (PMID 29075409, 2017). "In line with our observations in the pancreases from patients with diabetes, exposure of islets to diabetogenic conditions in vitro led to a loss of Siglec-7 expression, in particular, treatment of islets with a mixture of 22.2 mM glucose/0.5 mM palmitate as well as with the cytokines IL-1β/IFNγ." (PMID 28378743, 2017). "HMGB1 is a typical DAMP that engages TLR4 to activate NF‐κB and prime the NLRP3 inflammasome, thereby amplifying IL‐1β–driven inflammation; diabetes‐related AGEs and ROS further potentiate NLRP3 activation and pyroptosis, delaying epithelial repair." (PMID 41503166, 2026). "In conclusion, our study demonstrates that topical application of rTMD1 enhances corneal wound healing in diabetes by inhibiting HMGB1/TLR4/NLRP3/IL‐1β–mediated inflammation." (PMID 41503166, 2026). "Prior studies show that hyperglycemia augments pro-inflammatory cytokine secretion and that IL1B is a key driver of chronic low-grade inflammation in diabetes." (PMID 41516018, 2025). "Interleukins such as IL-1β, IL-6, and IL-10 emerge as central mediators in β-cell dysfunction, chronic inflammation, insulin resistance, and the progression of diabetes-related complications." (PMID 40804870, 2025). "Inflammatory cytokines such as TNF-α, IL-1β, and IL-6 activate multiple signaling pathways, leading to insulin resistance, impaired insulin secretion, and promotion of diabetes and its complications." (PMID 41306290, 2025). "Diabetes has been linked to elevated levels of plasma TNF, IL-1b, interleukin 6 (IL-6), interferon-g (IFNg), and PAI-1, as well as changes in immune cell responses, resulting in chronic low-grade inflammation." (PMID 40283013, 2025). "Treatment of rodent diabetes models with IL-1 signaling inhibitors or antibodies targeting IL-1β has also been shown to improve insulin sensitivity." (PMID 39940855, 2025). "Pro-inflammatory cytokines, such as tumor necrosis factor-alpha (TNF-α), interleukin-6 (IL-6), and interleukin-1β (IL-1β), are upregulated in individuals with diabetes, contributing to insulin receptor desensitization and impaired glucose uptake." (PMID 40563357, 2025). "One possible mechanism is the interplay between FGF-22 and pro-inflammatory cytokines, such as interleukin-1β (IL-1β), which are known to contribute to insulin resistance, beta-cell dysfunction, and vascular inflammation in diabetes." (PMID 40943671, 2025).
diabetes (continued). "Strong relationships exist between immune factors and hyperglycemia, particularly proinflammatory factors such as interleukin (IL)-1β protein levels and genetics, which significantly correlate with the development of type 2 diabetes mellitus (T2DM)." (PMID 41137275, 2025). "Patients with type 2 diabetes mellitus have higher plasma concentrations of pro-inflammatory cytokines, including IL-1β, IL-6, IL-8, IL-17, IL-18, TNF-α, IFN-γ, and TGF-β, according to research (T2DM)." (PMID 40149566, 2025). "NETs in the setting of diabetes can also function as a stimulus for NLR family pyrin domain-containing 3 (NLRP3) inflammasome activation in macrophages to promote IL-1β-dependent exacerbation of inflammation." (PMID 39875729, 2025). "High glucose levels in diabetes promote macrophage polarization, leading to increased IL-1β release." (PMID 40332476, 2025). "The wound healing defect in SIRT4KO mice also parallels observations in metabolic diseases such as diabetes, where impaired macrophage function and elevated IL-1β contribute to poor tissue repair." (PMID 40463174, 2025). "In the current study, we found that diabetes impaired macrophage lipid metabolism during liver IR and caused more severe aseptic inflammation (TNF‐α, IL‐1β, IL‐6, and IL‐18)." (PMID 40778489, 2025). "Inflammatory cytokines, e.g., IL-1β, impair β-cell function and survival, contributing to diabetes pathogenesis by inducing stress, altering gene expression, driving dedifferentiation, and reducing insulin production." (PMID 41120257, 2025). "A study has shown that SB can reduce intestinal inflammation induced by diabetes mellitus, and the concentrations of IL-1β and TNF-α in mice that ingested SB decreased." (PMID 39997745, 2025). "ILs are the key contributors to retinal pathology in diabetes—in our previous study, we identified IL-6 and IL-1β as important mediators in DR progression." (PMID 40671907, 2025). "A subanalysis of the 40% of participants with diabetes showed that blocking IL-1β also significantly decreased HbA1c during the first 6–9 months of treatment, with the effect waning over the course of the study." (PMID 39496966, 2025). "NLRP3-driven production of IL-1β and IL-18 contributes to the tissue damage observed in various autoimmune and autoinflammatory diseases, such as gout, rheumatoid arthritis, type 2 diabetes mellitus, cardiovascular disorders, and infectious diseases." (PMID 40307577, 2025). "In diabetes, chronic inflammation—with elevated IL-6, IL-12, IL-1β, and other cytokines—directly suppresses BDNF expression and signaling." (PMID 41142318, 2025). "This includes inflammation driven by the inflammasome effector cytokine IL‐1β within plaque‐laden arterial walls during atherosclerosis and the impairment of insulin signaling during diabetes." (PMID 39327931, 2025). "It was previously indicated that the levels of proinflammatory cytokines, including TNF-α, IL-1β, and IL-6, are increased as diabetes progresses." (PMID 40589410, 2025). "Diabetes mellitus (DM) is characterized by chronic low-grade inflammation, with elevated baseline IL-1β and IL-6." (PMID 41158128, 2025). "Ursolic acid, a natural compound with anti-inflammatory properties for treating diabetes and Parkinson’s disease, inhibits IL-1β secretion, pyroptosis, and ASC speck formation in mouse glomerular mesangial cells." (PMID 40307577, 2025). "Hyperglycemia further aggravates this process by significantly upregulating pro-inflammatory cytokines such as NF-κB-p65, IL-1β, and IL-6, thus reinforcing chronic inflammation and contributing to diabetes-related pathologies." (PMID 41142063, 2025). "It is also known that diabetes induces IL-1β expression in many different cell types, especially macrophages." (PMID 40917299, 2025). "Rodent studies further support these findings, showing that IL‐1β is upregulated following streptozotocin (STZ)‐induced diabetes." (PMID 41164346, 2025).
diabetes (continued). "In Medalists, education, exercise, and waist/hip ratio associated with higher volumes in most regions, while female sex, increasing age, diabetes duration, HDL, total cholesterol, IL-1β, and lower visual acuity associated with lower brain volumes." (PMID 39883521, 2025). "Levels of PGE2 and IL-1β in gingival crevicular fluid from diabetes patients with matched periodontitis severity were significantly higher than those in non-diabetic individuals." (PMID 39193343, 2024). "It has been reported that miR-9-5p can mitigate diabetes by downregulating pyroptosis, which is coupled with reductions in IL-1β, IL-18, NLRP3, and Caspase-1." (PMID 38934781, 2024). "The model to predict SF-12 physical at 2-weeks had an R2 = 0.20 and included IL-1β (p = 0.01) and diabetes (p = 0.02) as significant predictors, such that higher IL-1β and reporting comorbid diabetes worsened SF-12 physical score at 2-weeks." (PMID 38702410, 2024). "The observation of significant IL-1β upregulation in experimental diabetic retina pointed to IL-1β as a possible mediator of the acute-phase response raised by activated Müller cells." (PMID 39765697, 2024). "Diabetes is frequently associated with elevated levels of inflammatory cytokines (e.g., TNF-α, IL-1β, and IL-6) and AGEs, which have been linked to the pathophysiology of both diabetes and OA." (PMID 39139325, 2024). "According to the results of IL‐1β ELISA in the serum, the highest amount of IL‐1β was detected in the diabetes group." (PMID 39479688, 2024). "IL‐1β cytokine levels decreased significantly in the diabetes +25 mg/kg bW stevia group compared to the diabetes group (**p < .01)." (PMID 39479688, 2024). "It has been shown to reduce the levels of pro-inflammatory cytokines such as IL-1β, IL-6, and TNF-α, which are associated with insulin resistance and chronic inflammation in diabetes." (PMID 39092264, 2024). "The model to predict SF-12 physical at 2-weeks had an R2 = 0.23 and included IL-1β (p = 0.01) and diabetes (p = 0.02) as significant predictors, such that higher IL-1β and reporting diabetes reduced SF-12 physical scores at 2-weeks." (PMID 38702410, 2024). "In type 2 diabetes mellitus, IL-1β has previously been shown to regulate the recruitment of NF-κB and STAT1 transcription factors to the promoter region." (PMID 38891092, 2024). "While IL‐1β promotes insulin resistance and diabetes, IL‐18 regulates energy expenditure and food intake." (PMID 38629728, 2024). "The administration of a rat-specific IL-1β monoclonal antibody to the diabetic Cohen rat, a genetic model of nutritionally induced diabetes when fed a sucrose-rich diet, counteracted beta-cell dysfunction and glucose intolerance." (PMID 39120275, 2024). "The inflammation that occurs in adipose tissue due to the release of TNF-α, IL-1β, and IL-6 is a crucial factor in the development of cardiovascular disorders, diabetes, and cancers." (PMID 38317220, 2024). "In diabetes induced animal model, the leaf extract reduced the circulatory levels of inflammatory markers such as Interleukin-1 beta (IL-1β), Interleukin 6 (IL-6), and TNF-α." (PMID 39479139, 2024). "HGF has anti-inflammatory properties; it can increase IL-10 levels and reduce IL-1β levels in pancreatitis or diabetes." (PMID 38533089, 2024). "Omega-1 reduces the development of diabetes in NOD mice by regulating an inflammasome-dependent IL-1β release and triggering Tregs production." (PMID 39481080, 2024). "The IL-1β antagonist anakinra has demonstrated the ability to increase blood sugar levels and beta cell production in individuals with diabetes and prediabetes." (PMID 39328924, 2024). "Anti-inflammatory treatments, including minocycline or baicalein, attenuate the upregulation of IL-1β and TNF-α and confer retinal protection in animal models of diabetes as demonstrated by reductions in neuronal loss, capillary loss, and vascular leakage." (PMID 40603568, 2024).